CCL5 (C-C motif chemokine ligand 5)
Diseases named in the same sentence as CCL5 in open-access papers (continued):
Sharing a sentence is not in itself a finding about the gene and the disease.
cancer (continued). "The immunohistochemistry results demonstrated that the staining intensity of CCL5, CD3E and LCK in HCC cancer tissues ended to be decreased compared with those in normal tissues." (PMID 34218795, 2021). "During cancer progression, cancer cell-derived CCL2, CCL5, CXCL8, and CXCL5 are released and recruit immunosuppressive-myeloid cells into the TME, including MDSCs, TAMs, and TANs through CXCR2 activation." (PMID 35127700, 2021). "CCL5 can be a potential biomarker and therapeutic target in NPC based on a cancer cell line secretome profiling study." (PMID 34204797, 2021). "Our study first reported the carcinogenic and cancer‐promoting effects of TMEM92‐AS1 in GC and showed that TMEM92‐AS1 regulated the expression of CCL5 by binding to YBX1 to exert function." (PMID 33247987, 2021). "Among the identified DEGs, 5 candidate cancer-induced genes including BHLHE40, AREG, SOCS1, CCL5 and DDIT4 were selected for external validation on an independent set of PBMC samples of patients with various stages of HCC." (PMID 34045534, 2021). "The results reveal different networks in each group with IL-10 and Rantes/CCL5 clusters on control samples and GMCSF and IL-6 in cancer." (PMID 35048057, 2021). "Paget postulated that various cytokines secreted from cancer cells, including CCL2, CCL5, and interleukin-6, and a specific microenvironment communicates to attract cancer cells toward specific organs." (PMID 33806911, 2021). "In multiple dataset validations, the expression levels of CCL5, CXCR6, CD3E, and LCK were decreased in cancer tissues." (PMID 34218795, 2021). "They impact on cancer metastasis through releasing soluble factors such as chemokine SDF-1, IL-6 and CCL5." (PMID 33838662, 2021). "Accordingly, we observed increased expression of IFNG-related genes in the CD8HIGH HPV+ subset, e.g., CCL5, CXCL9/13, CXCR6, and HLA-DRA, which contribute to a pan-cancer signature suggested to predict an optimum response to anti-PD1 immune checkpoint-therapy." (PMID 34771506, 2021). "CCL5 increases the secretion of MMP-9, which degrade basal membrane and extracellular matrix, promoting cancer cell motility and metastasis." (PMID 34112253, 2021). "Similar analysis including IL-1β, Rantes/CCL5, MCP1, GMCSF, TNFα, and IL-6 showed similar results with elevated IL-6 increasing the probability of having a cancer diagnosis (p < 0.0046)." (PMID 35048057, 2021). "Specifically, we discovered that IFITM3 was positively correlated with the expression of critical immunomodulators, such as CCL5, CXCL9, and CXCL10, as well as the activities of the cancer-immunity cycle." (PMID 34456915, 2021). "CCL5 action is mediated through its receptors, C-C chemokine receptor (CCR) 1, CCR3 and CCR5, and carcinoma cells have different expression patterns of these chemokine receptors." (PMID 33671956, 2021). "Among those we found TNFSF13: FAS and CCL5: CCR5, two pairs of ligands/receptors that are known to play a role in AML and other cancers." (PMID 32399572, 2020). "In other cancers, the CCL5/CCR5 interaction deregulates β-catenin, which stimulates the invasiveness of cancer cells." (PMID 32260550, 2020). "Several CC chemokines CCL5 and CCL18 also promote EMT, cell migration and invasion in co-culture experiments involving TAMs and different cancer cells." (PMID 33414786, 2020). "Therefore, it might be safe to say that host CCL5 plays important roles in controlling cancer development but might create either pro- or anticancer environments according to the given situation, such as the type of cells that produce CCL5 and the type of cancers." (PMID 32218434, 2020). "While CCL14 and XCL1 have shown only good prognostic value, other chemokines such as CCL5, CCL20/CCR6, CCR7, CXCL1, CXCL8, and CXCL12/CXCR4 have consistently played the role of poor prognostic markers in different kinds of cancer." (PMID 31991604, 2020).
cancer (continued). "The picture seems to be more complex in the case of axes including CCL5 and CCL3, and their shared receptors CCR1 and CCR5 in regulating bone remodeling in cancer." (PMID 32582148, 2020). "Next, we used cBioPortal to evaluate the correlations between the levels of FGL2 and the cancer-promoting cytokines measured above (IL-10, MMP9, CCL5, TIM-3, IL-13, VCAM1, M-CSF and FGF-7) in ESCA tissues." (PMID 33323552, 2020). "Recent findings demonstrate that one NK cell population possesses potent cytolytic activity against targeted cancer cells, while others uniquely secrete various inflammatory cytokines (IFN-γ, TNF-α, and GM-CSF) and chemokines (CCL3 and CCL5)." (PMID 32231116, 2020). "CCL5 is known to enhance binding of leukocytes and T cells via CD44 signaling, an adhesion molecule common in many cancers." (PMID 32252260, 2020). "Evidence in the same direction was obtained in colorectal cancer, where macrophage-derived CCL5 acted through p65-STAT3 complexes that bound the COP9 signalosome promoter, giving rise to PD-L1 stabilization and up-regulation in the cancer cells." (PMID 32582148, 2020). "Hypoxia promoted cancer cell production of more macrophage chemokines, and among all increased chemokines (CCL2, CCL5, CCL8, CCL19, CCL21, and CXCL1), CCL8 was the most increased according to qRT-PCR detection." (PMID 31263103, 2019). "CAFs produce autocrine and paracrine cytokines, chemokines and growth factors like CXCL1, CCL5, HB-EGF and TGF-α, subsequently promoting cancer cell invasiveness through upregulation of matrix metalloproteinases (MMPs) and induction of EMT." (PMID 31888563, 2019). "There have been many studies investigating the link between CCL5/CCR5 and CRCs as well as other cancers." (PMID 31505877, 2019). "As for cancer treatments, various CCR5 antagonists, including maraviroc, vicriviroc, TAK-779, Met-CCL5, and anibamine, have been shown to have antitumor effect in preclinical mouse models." (PMID 30890699, 2019). "Together with CCL5/RANTES and CCL4/MIP-1β, RNS, IL-10, and TGF-β promote the recruitment and the immunosuppressive activity of Tregs, at least in cancer and in neonates." (PMID 30873175, 2019). "Many chemokines, including CXCL1, CCL2, CCL20, CCL4, CCL5, and XCL1, which are produced by both cancer and immune cells, drive BDCA3+ cDC1 recruitment into TME with the potential to induce local cytotoxic T cell function." (PMID 31484464, 2019). "Of these six genes, we found four to be significantly correlated with CTL levels across nearly all cancer lineages: CXCL9, CXCL10, CCL5, and IL16." (PMID 29615613, 2018). "In the same study, they also reported that chemokine CCL5 is up-regulated, and this specific CCL5–CCR5 axis can govern cancer cell metastasis in vivo and in vitro." (PMID 30619850, 2018). "For example, cancer cells stimulate expression of adipokines and adipocytokines (including IL-6, IL-1β, CCL2, CCL5, TNF-α, MCP-1, leptin), proteases, and inhibitors (e.g., MMP-11, PAI-1)." (PMID 28101337, 2017). "Some genes are important factors in the immune system of cancer patients, such as CCL2, CCL20, CCL5, CCR7, IFNG and P450 family." (PMID 28384236, 2017). "Till now, the relationship between paracrine effect of CCL5 and inherent EMT signaling in cancer cells has been poorly characterized." (PMID 28542126, 2017). "We demonstrated in this study that TNF-α-pretreated hMSCs secreted high levels of CCL5, through which communicated with CRC cells and enhanced cancer EMT and progression." (PMID 28542126, 2017). "There are reports shown that fibroblasts involve in the cross-talk of cancer cells and fibroblasts by secreting CCL2, CCL5, CXCL1, CXCL6, CXCL12, IL6, CXCL16 and others." (PMID 28465475, 2017). "A number of solid tumor types express CCL5 and/or CCR5, but only some malignancies were widely studied, thus providing evidence of the involvement of this pair in cancer progression and development." (PMID 24523569, 2014).
cancer (continued). "Particularly, after the cell-cell interactions, the chemokine CCL5 was abundantly secreted from BMMSCs and a function blocking antibody against CCL5 inhibited BMMSC enhanced cancer invasion area." (PMID 24204919, 2013). "In patient samples, however, the CCL5 expression was mainly detected in inflammatory cells in TME, some cancer cells and some sparse CAFs." (PMID 24204919, 2013). "For the sake of simplicity, in the following sections of the manuscript the four chemokines (CCL2, CCL5, CXCL8, CXCL10) will be referred together as “cancer-related chemokine cluster”." (PMID 24213226, 2012). "These cells were exposed to microenvironmental pressures, and the expression of a cancer-related chemokine cluster was used as readout for the malignancy potential (CCL2, CCL5, CXCL8, CXCL10)." (PMID 24213226, 2012). "Moreover, in IDC paths #1 and #2, marker genes for endothelial cells (VWF and PECAM1), lymphocytes (CD4), macrophages (CD68), chemokines (CXCL12 and CCL5), and chemokine receptors (CXCR4) were expressed highly at the intermediate stages of cancer progression." (PMID 39965034, 2025). "Additionally, IFN‐inducible chemokines CCL2, CCL5, and CXCL10 were found to be upregulated at both mRNA and protein levels in multiple cancer cells post‐irradiation." (PMID 40470716, 2025). "Furthermore, we found that MMP1/CCL5/ ALDH1A3, which have been identified as cancer‐promoting genes, were the downstream targets of the CPS1/PC‐PLC/DAG/PKC axis." (PMID 39387452, 2024). "In additional experiments, where we compared healthy mice to 4PYR-treated animals, we found that 4PYR has contributed to significantly increased expression of cytokines related to inflammation and cancer progression, such as CCL3, CXCL1, CCL5 or IL-1A and IL-1B." (PMID 39795893, 2024). "Several studies have evidently shown that chemokines (such as CCL2, CCL5, CXCL1, and CX3CL1) are involved in neuronal sensitization or microglia activation in the spinal cord, and some of these chemokines contribute to the development of cancer pain." (PMID 39641645, 2024). "Furthermore, in malignant tumors, CAFs promote tolerance by recruiting and inhibiting regulatory T cells through the secretion of CCL2, CCL5, etc.." (PMID 38612943, 2024). "Moreover, in the established highly metastatic cells, EMT induction was enhanced compared to that in the parent cell line, and CCL5 and IL-6 secreted during inflammation further enhanced EMT induction in cancer cells." (PMID 39126553, 2024). "To validate this hypothesis, we treated various cancer cell lines with TH1579 and observed a significant increase in the mRNA expression of the chemokines CCL5 and CXCL10 in NTUB1 and UMUC3 cells at 0.5 μM, and in A549 cells at 1 μM." (PMID 38796460, 2024). "Among them, CCDC28B showed strong positive and negative staining contrast in cancer cells, CCL5 exhibited moderate positive and negative staining contrast in cancer cells, and WT1 showed weak positive and negative staining contrast in cancer cells." (PMID 38676834, 2024). "In this study, we demonstrated the interaction between two important proinflammatory cytokines (CCL5 and IL-6) and cancer cells; however, no change in IL-6 expression was observed in RNA extracted from whole tumors." (PMID 39126553, 2024). "Additionally, MSCs are involved in the progression of cancer cells by releasing active molecules such as SDF-1, CCL5/CCR5, CCR2, TNF-α, TGF-β, etc.." (PMID 38022534, 2023). "In contrast, FMRP‐KO cancer cells could recruit CCR5+ and CXCR4+ CD8 T cells to indirectly kill cancer cells by promoting M1 macrophages to secrete proinflammatory chemokines CCL5, CXCL9, and CXCL10." (PMID 36968189, 2023). "The network between platelets, cancer cells, endothelial cells, and smooth muscle cells attracts monocytes into the early metastatic niches through chemokines such as CCL2 and CCL5 (known as regulated on activation, normal T cell expressed and secreted (RANTES))." (PMID 36831623, 2023).
cancer (continued). "In addition, the expression of CCL5 and CCR5 is related to an increase in cDC1s in the TME and the prolonged overall survival time of cancer patients." (PMID 37141250, 2023). "Several previous reports have documented the role of CCL5 and AREG in cancer progression." (PMID 37553567, 2023). "Further study on how the CCL5/CCR5 signaling axis acts on host immune cells and cancer cells to create an antitumor and anticancer microenvironment may provide useful insights into options for future drug development." (PMID 37141250, 2023). "In specific, TIS is referred to as an 18‐gene signature (CCL5, GZMK, CD3D, CD3E, CD2, HLA‐DRA, IL2RG, NKG7, CIITA, CXCR6, LAG3, TAGAP, HLA‐E, CXCL13, IDO1, CXCL10, STAT1, and GZMB), which was related to the response to ICIs in various cancers." (PMID 37434432, 2023). "TAM in TME secrete CCL5 which induces angiogenesis and EMT in cancer cells." (PMID 36761981, 2023). "Cancer cells release growth factors, such as FGF-2, VEGF, PDGF, EGF, TGFβ, and cytokines and chemokines, the core group consisting of CCL2, CCL5, IL-6, IL-8, as well as other soluble factors that activate fibroblasts and modulate CAF gene expression patterns and their metabolism." (PMID 37046676, 2023). "The 4T1/GFP spheroids (S) secreted CCL5 (53 pg/mL) and CXCL5 (290 pg/mL), which are associated with a negative cancer prognosis." (PMID 37445941, 2023). "Following this, another signaling loop is activated as well: CA-MSCs secrete CCL5, which binds to CCR5 on the surface of cancer cells and triggers the expression of the chemokine colony stimulating factor-1 (CSF-1) on those cancer cells, which then induces macrophages and MDSCs migration." (PMID 38022534, 2023). "As with TCGA Pan-Cancer Atlas data, patients with below-median PI24 scores expressed high levels of immunoglobulin genes, CD8A, and chemokine genes (CCL4, CCL5, and CXCL10), and had significantly higher PFS and OS rates (P = 0.00041 and P = 0.0011, respectively)." (PMID 36099049, 2022). "CCL5, XCL1, XCL2, CCL17, CCL22, and CCL19 showed a positive correlation with DEF6 in most cancers, and DEF6 may function in regulating these chemokines in cancer." (PMID 36686789, 2022). "Besides, high intratumoral expression of CCL5 is correlated with better prognosis and strongly correlated with intratumoral CD8A expression across multiple cancer types according to our analysis of TCGA datasets." (PMID 36352411, 2022). "CCL5 is expressed by cancer cells and CXCL9 is produced by immune cells in cancer tissue." (PMID 36618371, 2022). "Importantly, HLA-I+ cancer cells secreted sustained levels of the chemotactic factors CXCL10, CCL4, CCL5, and IFN-γ cytokine in contrast to the HLA-I– cancer cells." (PMID 35503263, 2022). "For cytokines, CCL5 is highly expressed in CD8 + T cells, NK Cells, NKT Cells, CD4 + T Memory Cells, Plasma Cells, and Langerhans Cells and strongly interacts with SDC1 and SDC4 in Cancer Cells, affecting cancer progression, development, and the survival." (PMID 36401283, 2022). "Taken together, these data show that the Macrophages-aPKCɩ-CCL5 loop could be a potential therapeutic target for CCA treatment, especially in cancers with high aPKCɩ expression levels." (PMID 35033156, 2022). "Cancer cells often maintain abundant damaged DNA, which can also stimulate STING-dependent induction of IFNs and other anti-tumor cytokines/chemokines, including CXCL10 and CCL5." (PMID 36498833, 2022). "Our results suggested that the combination of CDK4/6 inhibitor with CCL5 inhibitor or senotherapy could be considered to improve the curative effect and reduce the side effect of CDK4/6 inhibitors in the treatment of cancer." (PMID 37181790, 2022).
cancer (continued). "As a seven-transmembrane G protein-coupled receptor, CCR5 can bind to a variety of ligands CCL3 (MIP1α), CCL3L1, CCL4 (MP-1β), CCL5 (RANTES), CCL8 (MCP2), CCL11 (Eotaxin), CCL13 (MCP-4), and CCL16, which are reported to be highly expressed in most malignant tumors." (PMID 36167571, 2022). "These cells are also able to activate CD8+ cytotoxic T cells, which are the most potent anticancer immune effectors and constitute the foundation of current effective cancer immunotherapies through the secretion of the chemokines previously listed (CCL2, CCL3, CCL4, CCL5 and CXCL10)." (PMID 36325334, 2022). "Some studies indicated that macrophages exposed to hypoxia/lactate may secrete IL-6, TNF-α, CCL5 and CCL18, which favor glycolysis and boost synthesis of pro-glycogenic factors in TME in some cancers." (PMID 36362348, 2022). "Contrastingly, Aldh1a3, Ccl5, Ccl11 and Ccl7 expression were significantly higher in ALDH+ BCSCs (P2) as compared to bulk cancer cells (P0), indicating that our sorted populations were indeed pure and RNA sequencing was reflecting the expected characteristics of these BCSC populations." (PMID 35053617, 2022). "CCL5 and CCL4 were specifically expressed in B-0, which activate antigen presentation pathways and PD-L1/PD-1 immune checkpoints in cancer to recover the adverse effect of low CCL5 expression reducing the recruitment efficiency for cells in immune killing cascades (e.g., cDCs and CTLs)." (PMID 36131282, 2022). "Moreover, FLT3LG and CCL5 or CCR5 gene expression signatures correlate with an enhanced cDC1 signature and a favorable overall survival in patients with cancer." (PMID 33980589, 2021). "In addition, ECM components produced by CAFs and CAFs-derived cytokines including C-C motif chemokine ligand 5 (CCL5), IL6, and C-X-C motif chemokine ligand 10 (CXCL10) were found to regulate cancer cell metabolism by impacting on different signaling pathways." (PMID 34852849, 2021). "The chemokine CCL5, previously known as T-cell-specific protein RANTES-(regulated on activation, normal T-cell expressed, and secreted), is a CC chemokine ligand, both known for its role in inflammatory diseases and in cancer progression." (PMID 33923334, 2021). "In addition, MSCs enhance cancer metastasis through releasing soluble factors such as chemokine SDF-1, IL-6 and CCL5." (PMID 33838662, 2021). "By secreting CCL5, M2-TAMs may activate signal STAT3 leading to enhanced cancer cell proliferation and invasion/metastasis formation." (PMID 34638423, 2021). "Next, we analyzed the relationships of LCK with IFNG, CCL5, and CXCR3, using TCGA bulk RNA-sequencing data, and we found significant associations in the expression levels of LCK with IFNG (total rho=0.73), CCL5 (total rho=0.80), and CXCR3 (total rho=0.84) in most cancer types." (PMID 35069521, 2021). "Among the many SASP factors, IL-6, CCL5, CXCL12, CCL2 and IL-8 have a particularly important role in supporting cancer cell metastasis formation and the establishment of an immunosuppressive microenvironment, although in some cancer models they can be found in the immune stimulatory secretome." (PMID 34079557, 2021). "In addition, the CCL5/CCR5 signaling pathway is involved in the interaction between MSCs and cancer cells." (PMID 34001269, 2021). "According to the scoring criteria as described in the Materials and Methods, 35% (39 out of 111 case), 19% (21 out of 111 cases), 65% (72 out of 111 cases) and 41% (45 out of 111 cases) were considered positive for CCL5 in stromal cells and CCR1, 3 and 5 in carcinoma cells, respectively." (PMID 33671956, 2021). "CCL5 and CCR5 are involved in the growth, progression, and metastasis of various cancers." (PMID 32260550, 2020). "Additionally, we sought to elucidate the mechanisms responsible for microglia Ccl5 production and LGG cancer cell growth." (PMID 32358581, 2020).